STAT3 (signal transducer and activator of transcription 3)
Diseases named in the same sentence as STAT3 in open-access papers (continued):
Sharing a sentence is not in itself a finding about the gene and the disease.
diabetes (continued). "Interestingly, diabetes seems to alter cardiac STAT3 signaling, lowering its activation at the S727 site in both in vivo and in vitro models, even if in some other cases, increased activation of canonical STAT3 was observed in diabetic animals." (PMID 34642818, 2021). "Our study results indicate that MBNL1, miR-130a-3p, and STAT3 may become new targets for treating diabetic renal tubular lesions." (PMID 32104542, 2020). "Moreover, tumor tissues from CCA patients with diabetes mellitus showed increased levels of phospho-STAT3, confirming the link between high glucose patient blood and STAT3 activation." (PMID 32138158, 2020). "However, in diabetes, the cardiac Cav-3 expression is impaired by hyperglycemia-induced oxidative stress, accompanied with lower activation of Akt and STAT3, while the diabetic hearts are more vulnerable to I/R injury and less responsive to RPC." (PMID 31583053, 2019). "Moreover, streptozotocin(STZ)-induced diabetes of transgenic mice with reduced STAT3 activity develop less proteinuria, glomerular cell proliferation, and fibrotic activities than normal mice." (PMID 31699972, 2019). "While diabetes is a complex disease, and STAT3 can be phosphorylated by many cytokines that utilize the gp130 receptor, it appears that hyperglycemia (but not hyperosmolarity) is sufficient to increase IL-6-induced STAT3 phosphorylation in keratinocytes in vitro." (PMID 31073533, 2019). "We previously demonstrated impaired Cav-3 expression (a dominant constituent protein of cardiomyocyte caveolae formation) and reduced phosphorylation of Akt and STAT3 in diabetic hearts, which was attributable to decreased tolerance to myocardial I/R injury in diabetes." (PMID 31583053, 2019). "Thus, studying involvement of STAT3 in myocardial fibrosis specifically during diabetes presents a particular prominent interest for understanding DCM." (PMID 31709266, 2019). "Antioxidant treatment with NAC could restore RPC-induced cardioprotection in diabetes by improving Cav-3-dependent Akt and STAT3 activation and by facilitating the cross talk between PI3K/Akt and JAK2/STAT3 signaling pathways." (PMID 31583053, 2019). "Previous reports of individuals with monogenic autoimmunity have shown that many do not develop diabetes (e.g. 70% of those reported to have gain-of-function STAT3 mutations are not diabetic)." (PMID 29417186, 2018). "Recently, some promising agents have been suggested to prevent STAT3 dysregulation in diabetes." (PMID 30424579, 2018). "The reasons for these controversies are unclear and may include substantial differences in the method of induction, type, severity, and duration of diabetes as well as differences in the method of detection of STAT3 phosphorylation and expression." (PMID 30424579, 2018). "Hyperglycemia, a central condition in the pathogenesis of diabetes, induces the activation of the signal transducer and activator of transcription 3 (STAT3) signaling pathway, which is integral to various types of tissue damage, including myocardial dysfunctions." (PMID 28672855, 2017). "In the early-middle stages of diabetes, the levels of STAT3 and SOCS3 in the retinas are increased." (PMID 29318137, 2017). "However, other studies reported that cardiac Stat3 and phospho-Stat3 expression were increased in diabetes leading to hypertrophy." (PMID 27496100, 2016). "Recent studies indicated that the inability of insulin to restore sevo-postC cardioprotection in diabetes might be attributed to diabetes-induced STAT3 mediated inhibition of PI3K signaling." (PMID 26783539, 2016). "Diabetes showed significantly decreased p-STAT3 when compared with control group." (PMID 26783539, 2016). "We postulated that reductions in myocardial HO-1 and STAT3 in diabetes may be a consequence of reduction in cardiac Brg1 expression subsequent to hyperglycemia-induced oxidative stress." (PMID 23853776, 2013).
diabetes (continued). "NAC may have increased STAT3 phosphorylation in diabetes through enhancing Brg1 expression, although further study is needed to confirm this hypothesis." (PMID 23853776, 2013). "Therefore, in addition to exploring the changes of myocardial Brg1 protein in diabetes, we also investigated the myocardial protein levels and phosphorylation/activation status of STAT3 in diabetic heart." (PMID 23853776, 2013). "Enhancement of cardiac Brg1 expression may thus represent a novel mechanism whereby NAC enhanced cardiac HO-1 and p-STAT3 expressions and attenuated cardiac diastolic dysfunction in diabetes." (PMID 23853776, 2013). "Furthermore, it has recently been demonstrated that rosiglitazone attenuates diabetes-induced apoptosis in retinal neurons of STZ-induced diabetic rats by inhibition of phospho-STAT3 (p-STAT3) and cytokine signaling 3 (SOCS3)." (PMID 23431285, 2013). "This activating STAT3 variant results in the decrease of insulin expression by repressing the transcriptional activity of ISL1, which could be involved in the pathogenesis of pancreatic β‐cell dysfunction and early‐onset diabetes." (PMID 38404237, 2024). "Since confounding factors such as age, sex, diabetes, and hypertension/hypertrophy may alter the benefits provided by the activation of the RISK and SAFE pathway, here we consider possible effects that these unfavorable factors may have on cardiac STAT3." (PMID 34642818, 2021). "However, it remains unclear whether the compromised RPC cardioprotection in diabetes is an independent manifestation of hyperglycemia-induced oxidative stress or linked to impaired Cav-3 expression and PI3K/Akt and JAK2/STAT3 signaling." (PMID 31583053, 2019). "As expected, S3I-201 treatment prevented the diabetes-associated increased phosphorylated STAT3 without affecting total STAT3 levels, western blot analysis of kidney tissues of the diabetic mice corroborated the inhibitory action of S3I-201 on STAT3 phosphorylation." (PMID 31699972, 2019). "Furthermore, using the LysMCre/+SOCS3fl/fl mice, where the myeloid cells constitutively express pSTAT3 due to the deletion of its inhibitor SOCS3, we showed that uncontrolled STAT3 activation in myeloid cells leads to more severe diabetes-induced retinal vascular changes." (PMID 31286987, 2019). "Hepatic STAT3 signalling had been identified to be essential for normal glucose homoeostasis and disrupting this signalling pathway could contribute to the onset and progression of diabetes." (PMID 23750710, 2013). "Therefore, the current study was designed to test the hypothesis that myocardial Brg1 is reduced in diabetes and antioxidant NAC may enhance cardiac Brg1 expression and concomitantly increase cardiac STAT3 activation and confer cardioprotection in diabetes." (PMID 23853776, 2013). "It was found that nine active ingredients in sweet potato leaves act on 90 targets related to diabetes, with the main targets for their blood glucose-lowering effects being AKT1, GAPDH, STAT3, TNF, and EGFR." (PMID 41515064, 2026). "Diabetes will be analyzed as a dichotomous variable, while IL-6/GP130/JAK/STAT3 activation will be treated as a continuous variable." (PMID 41397158, 2025). "Our data shows that ALA activated AMPK while inhibiting STAT3 phosphorylation in both HG/PA-treated H9C2 cells and mice with STZ-induced diabetes." (PMID 41515376, 2025). "Beyond oncology, ANGPTL4 has also been implicated in STAT3 regulation in polycystic ovary syndrome and diabetes, indicating its broader role in modulating JAK/STAT3 signaling across diseases." (PMID 40616161, 2025). "The microRNA miR-221-3p inhibits the inflammatory response and promotes skin wound healing in diabetes by targeting DYRK1A expression, thereby regulating the DYRK1A/STAT3 signaling pathway." (PMID 38461326, 2024). "Among the top 20 core targets, 5 targets (STAT3, PIK3CA, AKT1, EGFR and VEGFA) were closely related to diabetes." (PMID 38921004, 2024).
diabetes (continued). "In conclusion, we demonstrated that miR-221-3p inhibited the inflammatory response and promoted skin wound healing in diabetes by targeting DYRK1A expression and then regulating the DYRK1A/STAT3 signaling pathway." (PMID 38461326, 2024). "Our study shows that miR-221-3p regulated the STAT3 signaling pathway by targeting DYRK1A, inhibiting the keratinocyte inflammatory response and accelerating wound healing in diabetes." (PMID 38461326, 2024). "In the KEGG pathway map, the AGE-RAGE signaling pathway in diabetes complications includes AKT, IL-6, STAT3 and other targets, which all play an important regulatory role in the AGE-RAGE pathway." (PMID 37745719, 2023). "In the comparison of the early Stages I and II Endometrial Cancer with the Benign Gynecology Control Group, several processes commonly deregulated in both endometrial cancer and diabetes were identified: EMT, PTEN/PI3K, and STAT3." (PMID 35328698, 2022). "Interleukin-6 (IL-6), an inflammatory mediator produced by diabetes, activates the JAK-signal transducer and activator of transcription 3 (STAT3) signaling pathway." (PMID 36497173, 2022). "GCG, IRS1, VEGFA, STAT3, CCL2, CASP3, and APOE as diabetes mellitus-related proteins and SREBF1, LPL, PPARA, APOB, GPT, MAPK8, and FASN as NAFLD-specific proteins were identified as possible discriminating factors between the two studied diseases." (PMID 35154608, 2021). "The data showed that compared with the control group, the expression levels of CASP3, VCAM-1 and HGF were down-regulated in patients with syphilis and diabetes, while ALB, FN1, MMP9, IL8, CTGF, STAT3 and IGF1 were up-regulated." (PMID 32342229, 2020). "Consistent with previous study, diabetes led to the activation of STAT signalling pathway, as assessed by STAT1 and STAT3 tyrosine phosphorylation." (PMID 30955247, 2019). "In summary, the current results demonstrate that hyperglycemia-induced oxidative stress is involved in the impaired Cav-3-modulated PI3K/Akt and JAk2/STAT3 signaling, which ultimately compromises RPC cardioprotection in diabetes." (PMID 31583053, 2019). "To further understand the role of pSTAT3 in diabetes-induced myeloid cell activation, we used LysMCre/+SOCS3fl/fl mice, in which SOCS3 was deleted in myeloid cells resulting in spontaneous STAT3 activation." (PMID 31286987, 2019). "In a rat model of diabetes induced by a high-glucose and -fat diet + STZ injection, enhanced phosphorylation of STAT3 due to diabetes was attenuated by losartan treatment." (PMID 30424579, 2018). "The combination of antioxidant N-acetylcysteine and allopurinol restored the decreased levels of p-STAT3 (Ser727, Tyr705) after ischaemia/reperfusion and so contributed to smaller infarct size in STZ-induced diabetes." (PMID 30424579, 2018). "Some drugs used to treat diabetes or DR, such as statins, enalapril, and tazones, decrease SOCS3 and STAT3 expression in diabetic animals." (PMID 29318137, 2017). "In fact, high glucose levels induce angiotensin II-dependent activation of Jak2, Stat1, Stat3, and Stat5 and increase of TGF-β and fibronectin synthesis in rat mesangial cells of streptozotocin-induced diabetes." (PMID 26872211, 2016). "Particularly, the anti-inflammatory effect of PEBP is pointing out to the blockade of the STAT3 pathways (essential in CSCs, and inflammation) and the activation of AMPK, which in turn inhibits MAPK downstream (essential in diabetes and cancer)." (PMID 26762586, 2016). "Therefore, we implement NAC treatment to 8-week diabetic rats during feeding period and sevo-postC before reperfusion to test the hypothesis that NAC and sevo-postC can synergistically reduce myocardial IRI in diabetes and explore the roles of p-STAT3, FoxO1, APN, and CD36 in this procedure." (PMID 26783539, 2016).
diabetes (continued). "Elevated levels of activated Stat3 (p-Stat3) were shown to initiate Myostatin-mediated muscle wasting and inflammation in patients with CKD or diabetes via increase in C/EBP δ levels." (PMID 26257645, 2015). "Additionally, the three disease targets with the highest connectivity values in the string network, STAT3, BCL2, and AKT1, also mediate multiple diabetes-related signaling pathways and are key targets in the treatment of diabetes." (PMID 40733369, 2025). "The symptoms of diabetes may be modulated by regulating insulin and insulin growth factor (IGF) levels, which activate the JAK/STAT3 pathway." (PMID 39188680, 2024). "To compare STAT3 expression between healthy and T2D macrophages, we analyzed scRNA-Seq in human wound tissue isolated from patients without diabetes and those with T2D." (PMID 39435663, 2024). "Studies have revealed that diabetes can further impair the phosphatidylinositol 3-kinase/Akt/eNOS (PI3K/Akt/eNOS) pathway and activate JAK/STAT3 signaling, thereby exacerbating myocardial ischemia-reperfusion injury in diabetic rats which can be attenuated by treatment with SAA." (PMID 38283744, 2023). "The diabetes-induced decrease of Cav-3 expression may lead to caveola dysfunction, which plays a vital role in affecting PI3K/Akt and JAK2/STAT3 signaling in diabetic hearts." (PMID 31583053, 2019). "Under non-ischemic cardiac conditions, the effect of diabetes on the expression, phosphorylation, and activation of cardiac STAT3 is controversial." (PMID 31709266, 2019). "Deletion of the negative regulator of STAT3, the suppressor of cytokine signalling 3 (SOCS3) in myeloid cells, resulted in increased pSTAT3 expression and uncontrolled diabetes-induced leukocyte activation, increased leukostasis and exaggerated retinal vascular degeneration." (PMID 31286987, 2019). "In conclusion, the decrease in STAT3 phosphorylation/activation in post-ischemic hearts due to diabetes represents a definitive response regardless of the model." (PMID 31709266, 2019). "The exact mechanism of interplay between IL-6, STAT3, and SOCS3 at an organismal level during diabetes is likely complex; thus, it was of interest to determine if hyperglycemia itself might mediate altered IL-6R function in keratinocyte culture." (PMID 31073533, 2019). "Based on a literature review, the effect of diabetes on non-ischaemic baseline expression, phosphorylation or activation of cardiac STAT3 protein seems to be rather controversial." (PMID 30424579, 2018). "In summary, this study demonstrated that, in the early stage of STZ-induced diabetes, rats displayed increased myocardial oxidative stress and reduced antioxidant capacity together with impaired Akt/GSK-3β and STAT3 activation, which rendered the diabetic heart more sensitive to IRI." (PMID 24041262, 2013). "Myocardial STAT3 is an important transcription factor in the SAFE pathway (i.e., JAK2/STAT3 signaling cascade), especially during myocardium ischemia reperfusion injury, but cardiac p-STAT3 is reduced in diabetes." (PMID 23853776, 2013). "In the present study, we have investigated the effects of diabetes on the development of laser-induced CNV in mice, and we have also investigated the roles that oxidative stress and STAT3 signalling play in the regulation of VEGF in RPE cells in a high glucose environment." (PMID 23094067, 2012). "It has been suggested that diabetes-related oxidative stress may induce vascular IL-6 expression and activate IL-6R and gp130, which in turn activates the JAK2/STAT3 signaling cascade." (PMID 22553973, 2012).
diabetes (continued). "Moreover, several other genes between PECAM-1 and Igf2Bp1, such as Growth Hormone, STAT3, and STAT5 are involved in diabetic nephropathy or diabetes and an identified IDD4 interval spans STAT3." (PMID 16371158, 2005). "The resistance of effector T cells to the inhibition of regulatory T cells is one of the characteristics of the development of diabetes, and this resistance is related to the STAT3 signaling pathway but not to the ability of effector T cells to produce or respond to IL-6." (PMID 38800484, 2024). "Thus, our study showed that miR-221-3p inhibits the synthesis of inflammatory factors in skin wounds generated in an animal model of diabetes and that the infiltration of immune cells such as neutrophils and macrophages is mediated through the DYRK1A/STAT3 signaling pathway." (PMID 38461326, 2024). "It has been put forward that Stat3 activation can induce the production of the cytokine transforming growth factor-β1 (TGF-β1), and it responds to intracellular ROS, and oxidative stress that may be a major contributor to diabetes." (PMID 31461977, 2019). "Furthermore, in a Sprague-Dawley rat model of STZ-induced diabetes, a significant increase in non-ischaemic baseline STAT3 activation has been reported." (PMID 30424579, 2018). "Therefore, using a model of myocardial injury in type 2 diabetic mellitus (T2DM) rats, the aim of this study was to investigate the potential effect of OMT on myocardial injury and elucidate the role of the Nrf2/HO-1 and JAK2/STAT3 signaling pathways in diabetic rats." (PMID 36597092, 2023). "GCG, IRS1, VEGFA, STAT3, CCL2, CASP3, and APOE are the 7 DEPs that are related to diabetes mellitus as specific proteins but not seen among the central proteins of fatty liver disease." (PMID 35154608, 2021). "Few preclinical experiments have focused on the effect of SGLT2 inhibitors on MI without diabetes, and the proposed mechanisms were lowering intracellular Na+ and Ca2+, NHE inhibition, STAT3 and AMPK activation, CamKII inhibition, reduced inflammation, oxidative stress or modulate autophagy." (PMID 36891270, 2023). "Although the precise mechanisms by which hyperglycemia-induced inhibition of Akt and STAT3 activation compromise RPC-induced cardioprotection are not fully understood, the reduced expression of Cav-3 during hyperglycemia in diabetes might be a major factor." (PMID 31583053, 2019). "Thus, STAT3 modulation and β-cell ablation nonadditively enhance α-to-β reprogramming induced by PDX1, which may lead to the establishment of cell therapies for curing diabetes." (PMID 36496541, 2022).